ASIC3 (acid sensing ion channel subunit 3)
Description:
Forms pH-gated heterotrimeric sodium channels that act as postsynaptic excitatory receptors in the nervous system. Upon extracellular acidification, these channels generate a biphasic current with a fast inactivating and a slow sustained phase. ASIC3 is more sensitive to protons and gates between closed, open, and desensitized states faster than other ASICs (By similarity). Displays high selectivity for sodium ions but can also permit the permeation of other cations. As a neuronal acid sensor, probably contributes to mechanoreception, acid nociception, and heat nociception (By similarity). By forming heterotrimeric channels with ASIC2, generates a biphasic current with a fast inactivating and a slow sustained phase, which in sensory neurons is proposed to mediate the pain induced by acidosis that occurs in ischemic, damaged or inflamed tissues (By similarity).
Synonyms: ACCN3; DRASIC; SLNAC1; TNAC1
Tractability: Small molecule: a high-quality ligand is known; it belongs to a druggable protein family. Antibody: UniProt places it where antibodies can reach, with high confidence; its Gene Ontology location is reachable by antibodies, with high confidence; UniProt predicts a signal peptide or a membrane-spanning region. PROTAC: a small molecule that binds it is known.
Target class: Ion channel; Ligand-gated ion channel; Acid-sensing ion channel
Gene: Protein-coding gene on chromosome 7 (151,048,292 to 151,052,756, forward strand). Ensembl gene ENSG00000213199.
Subcellular location: Cell membrane; Cytoplasm
Subcellular location (Human Protein Atlas): Cytosol; Nucleoplasm
Pathways (Reactome):
Transport of small molecules: Stimuli-sensing channels
Gene Ontology:
Molecular function: pH-gated monoatomic ion channel activity; pH-gated sodium channel activity; protein binding; ligand-gated sodium channel activity; sodium channel activity; monoatomic cation channel activity; monoatomic ion-gated channel activity
Biological process: membrane depolarization; sensory perception of sour taste; detection of chemical stimulus involved in sensory perception of pain; sodium ion transmembrane transport; sodium ion transport
Cellular component: plasma membrane; cytoplasm; membrane
Genetic constraint (gnomAD): Loss-of-function variants: 46 observed, 57.77 expected, observed/expected ratio (o/e) 0.8, 90% interval 0.63 to 1.02. The upper end of that interval is the gene's LOEUF score, 1.02, which puts it in group 4 of 6, group 1 being the genes least tolerant of losing a copy. Missense variants: 770 observed, 743.49 expected, observed/expected ratio (o/e) 1.04, 90% interval 0.98 to 1.1. Synonymous variants: 336 observed, 305.67 expected, observed/expected ratio (o/e) 1.1, 90% interval 1 to 1.2.
Homologues: Orthologues: chimpanzee ASIC3 (96% identical), macaque ASIC3 (95% identical), mouse Asic3 (83% identical), guinea pig ASIC3 (83% identical), pig ASIC3 (83% identical), dog ASIC3 (81% identical), rabbit ASIC3 (80% identical), rat Asic3 (78% identical), Caenorhabditis elegans acd-2 (22% identical), Caenorhabditis elegans mec-10 (22% identical), Drosophila melanogaster Nach (20% identical), Caenorhabditis elegans mec-4 (19% identical), and 20 more. Paralogues in human: ASIC1 (48% identical), ASIC2 (46% identical), ASIC4 (46% identical), ASIC5 (24% identical), SCNN1A (23% identical), SCNN1G (23% identical), SCNN1B (21% identical), SCNN1D (21% identical).
Diseases named in the same sentence as ASIC3 in open-access papers:
ASIC3 is named in the same sentence as 83 diseases in open-access papers, as found by Europe PMC text mining. Sharing a sentence is not in itself a finding about the gene and the disease. The quoted sentences say what the papers report.
ischemia (8 papers, 2006 to 2024). A hypoperfusion of the BLOOD through an organ or tissue caused by a PATHOLOGIC CONSTRICTION or obstruction of its BLOOD VESSELS, or an absence of BLOOD CIRCULATION. "In the process of NGF signaling, intracellular JNK and NF‐κB are found to be engaged in the effects of NGF on the activities of ASIC3 under the conditions of limb I/R injury and ischemia of PAD." (PMID 38312021, 2024). "As a result of increases in NGF and expression of NGF's TrkA receptor as well as ASIC3 in DRGs of ischemia limbs, our study further determined if NGF can affect the activities of ASIC currents at pH 6.7 with pre‐application of 100 ng/mL NGF for 24 h." (PMID 38312021, 2024). "This change results in sustained ischemia of distally located tissues and persistently decreased pH in this area, which activates Acid-Sensing Ion Channel-3 (ASIC3), responsible for transmitting pain signals." (PMID 35887276, 2022). "The selective ASIC3 antagonist A-317567 has also been found to be effective at preventing the neuronal responses to different concentration of metabolites suggesting that sensing ischemia requires both P2X and ASIC3 activity." (PMID 29311839, 2017). "Other models show significant increases in the expression of P2X3/4/5, ASIC3 and P2Y1, which have also been linked to muscle afferent function, pain manifestation and EPR modulation post ischemia." (PMID 29311839, 2017). "The acid sensitive ion channels TRPV1 (transient receptor potential vanilloid receptor-1) and ASIC3 (acid sensing ion channel-3) respond to tissue acidification in the range that occurs during painful conditions such as inflammation and ischemia." (PMID 16813657, 2006). "In addition to TRPV1, P2X3, and ASIC3, it needs to point out that other muscle afferents’ receptors including μ-opioid and thromboxane (TP) receptors are engaged in processing chronic ischemia of the hindlimb muscles." (PMID 22934005, 2012). "In the specific context of ischemia, total DRG ASIC3 mRNA expression is increased in different injury models, and the total number of ASIC3 positive cells in the DRG increases." (PMID 29311839, 2017). "The findings further suggest that NGF is likely responsible for enhanced TRPV1, P2X3, and ASIC3 and plays a role in modulating the metaboreceptor component of the EPR in the hindlimb muscle ischemia." (PMID 22934005, 2012). "Overall, those accumulated data are helpful for elucidation of the roles played by ASIC1a and ASIC3 in modulating the EPR in I/R injury and ischemia seen in PAD and suggest that the levels of muscle pH should be considered for explanation of the experimental findings." (PMID 38312021, 2024). "Taken together, those results may be useful to clarify the role of ASIC1a and ASIC3 in regulating the exaggerated exercise pressor reflex in PAD rats with I/R injury and ischemia." (PMID 36967457, 2023).
Arthritis (7 papers, 2010 to 2022). Inflammation of a joint. "ASIC3 or TRPV1 deficiency attenuated arthritis-associated hyperalgesia in the chronic phase (after 6 or 8 weeks) and TDAG8 knockout attenuated the hyperalgesia in the acute and chronic phases, but TDAG8 knockdown only attenuated acute phase (before 4 weeks) of RA pain." (PMID 28827659, 2017). "Whether ASIC3 deficiency increases inflammation is arguable from previous studies using different arthritis models." (PMID 28827659, 2017). "Because ASIC3 gene expression was upregulated after intra-articular CFA injection, we investigated whether loss of ASIC3 gene reduced CFA-induced arthritis." (PMID 28827659, 2017). "ASIC3+/− mice showed a similar pattern as ASIC3+/+ mice in arthritis scores and hyperalgesia, except that arthritis scores in ASIC3+/− mice decreased at 8 weeks." (PMID 28827659, 2017). "ASIC3−/− mice showed less severe arthritis at 2 weeks (p = 0.043, compared to ASIC3+/+) but a similar peak level as ASIC3+/+ mice at 4 weeks." (PMID 28827659, 2017). "In a carrageenan-induced mouse arthritis model, the knee joint afferents with ASIC3 immunoreactivity increase from 31% to 50% after the induced joint inflammation, indicating that ASIC3 plays an important role in inflammatory joint pain." (PMID 27713310, 2010). "Several proton-sensing receptors, including transient receptor potential/vanilloid receptor subtype 1 (TRPV1), acid-sensing ion channel 3 (ASIC3), and proton-sensing G-protein-coupled receptors, were found to be associated with arthritis or arthritis-associated pain." (PMID 35408888, 2022). "The decrease of pH in arthritis may activate the ASIC3 channel expressed on DRG neurons which dominate the knee joint, thus transmitting pain signals to the spinal cord and brain and producing central sensitization." (PMID 33005097, 2020). "In the ASIC3−/− arthritis mouse model, synovial inflammation, bone erosion, and cartilage damage began to decrease from the 4th week, but bilateral hyperalgesia was decreased until the 6th week, indicating that ASIC3 is involved in chronic RA pain." (PMID 33005097, 2020). "Depletion of ASIC3 may have reduced arthritis-induced chronic pain in the late phase (after 6 weeks)." (PMID 28827659, 2017). "Consistent with a decrease in arthritis scores, the severity of synovial inflammation, bone destruction, and cartilage damage was attenuated in ASIC3−/− mice from 4 weeks, except that synovial inflammation and cartilage damage were not significantly reduced at 12 weeks." (PMID 28827659, 2017). "At 12 weeks, ASIC3 deficiency seemed to not fully suppress pannus, although it reduced arthritis scores and synovial macrophages (M1 type)." (PMID 28827659, 2017). "TDAG8, ASIC3, and TRPV1 influence arthritis scores and RA-induced hyperalgesia." (PMID 28827659, 2017). "However, further studies using ASIC3-deficient mice have suggested a more limited role in pain, as well as a proposed dual role of ASIC3 in arthritis where lack of ASIC3 ameliorates pain, but increases inflammatory processes in the arthritic joint." (PMID 32027884, 2020).
migraine (7 papers, 2017 to 2024). "As such, we propose that an ASIC3 or combined ASIC1/3 blocker may prove beneficial for the treatment of migraine and that ASIC‐dependent mechanisms may in part underlie the increased susceptibility of migraineurs to NO donors." (PMID 31975427, 2020). "ASICs, including ASIC and ASIC3, have potential as targets for the treatment of migraine, and inhibitors such as amiloride, mambalgin-1, and APETx2 that showed a promising alleviating mechanical allodynia effect in animal models." (PMID 38221631, 2024). "The study of Holton and colleagues demonstrates that blocking ASIC3, such as using APETx2, effectively inhibits sensitization of trigeminal nociceptive responses, which is potentiated by the migraine-triggering molecule NO." (PMID 38068897, 2023). "In relation to migraine, ASIC3 on dural afferents is thought to be a sensor of reduced extracellular pH within the dura." (PMID 38068897, 2023). "With regard to vascular functions of ASIC3, one contributing factor to migraine, as well as hypertension, is impaired activity of vascular smooth muscle cells (VSMC)." (PMID 33258401, 2021). "ASIC3 is expressed in the trigeminal ganglion and its response is potentiated by NO that can trigger migraine attacks in patients." (PMID 31975427, 2020). "It has been shown that ASIC3 plays an important role in various pain conditions such as inflammatory pain, postoperative pain, and migraine." (PMID 28754162, 2017). "Increasing evidence has shown that ASIC3 plays an important role in various pain conditions such as inflammatory pain, postoperative pain, and migraine." (PMID 28754162, 2017). "After pH stimulation, CGRP release is also increased in TG neurons via ASIC3 activation, which may result in neurogenic inflammation and migraine progression." (PMID 38068897, 2023). "Interestingly, VSMC isolated from cerebral arteries of mice express ASIC3 albeit to a lesser extent than other ASIC subunits and thus ASIC3 is expressed in cells whose dysfunction is associated with migraine and hypertension." (PMID 33258401, 2021). "Here, we demonstrate a clear translational potential for ASIC3 blockade in migraine." (PMID 31975427, 2020). "Given the ability of NO donors such as nitroglycerin to trigger migraine attacks reliably in patients and cutaneous allodynia/trigeminal sensitisation in rodents, our data suggest that this NO‐mediated effect may be at least in part be ASIC3‐dependent." (PMID 31975427, 2020). "Thus we sought to explore the potential therapeutic effect of ASIC3 blockade in migraine." (PMID 31975427, 2020). "As such, ASIC3 may play a key role in migraine pathophysiology and NO‐induced delayed migraine in patients, highlighting further the potential of targeted modulation of ASICs and the future development of mambalgins (peptides found in the venom of the black mamba) for migraine." (PMID 31975427, 2020). "Additionally, dural acidity leads to calcitonin gene-related peptide (CGRP) release from dural and trigeminal cell bodies and the release from trigeminal cell bodies can be blocked by a specific ASIC3 antagonist, suggesting a potential ASIC3-mediated role in migraine." (PMID 29549622, 2018). "This discovery supports the development of specific ASIC3 or combined ASIC1/3 blockers for the treatment of migraine-related pain and suggests a potential role in ASIC-dependent NO-mediated migraine triggering." (PMID 38068897, 2023). "In addition to ASIC3, other ASICs may also play a role in the development of migraine attacks." (PMID 38068897, 2023). "Although specific central effects cannot be ruled out as ASIC3 is expressed centrally, including in the hypothalamus (Meng, Wang, Chen, Xu, & Zhou, 2009) and trigeminal nucleus caudalis, where its expression is up‐regulated in a dural‐inflammatory mediated preclinical model of migraine." (PMID 31975427, 2020).
pancreatic cancer (7 papers, 2017 to 2024). "ASIC3 has an H+ gating function, which promotes the acid-induced epithelial-mesenchymal transition in pancreatic cancer cells." (PMID 35265613, 2022). "Significantly, although without obvious effect on proliferation, knockdown of ASIC1 and ASIC3 in pancreatic cancer cells significantly suppresses liver and lung metastasis in xenograft model." (PMID 28518134, 2017). "Together, these findings provide compelling evidence that ASIC1 and ASIC3-[Ca2+]i signaling pathway confers EMT capacity to pancreatic cancer cells in acidity condition." (PMID 28518134, 2017). "Western blot confirmed that the protein of ASIC1 and ASIC3 in pancreatic cancer cell lines was increased compared with normal pancreatic ductal cells." (PMID 28518134, 2017). "This study reports that ASIC1 and ASIC3 are mainly expressed on membrane of pancreatic cancer cells and upregulated in pancreatic cancer tissues." (PMID 28518134, 2017). "Taken together, our results provide strong evidence that ASIC1 and ASIC3 promote metastasis of human pancreatic cancer cells in vivo." (PMID 28518134, 2017). "After knockdown of ASIC1 and ASIC3 separately or simultaneously, the acidity-promoted invasion and migration of pancreatic cancer cells were inhibited." (PMID 28518134, 2017). "This study indicates that ASIC1 and ASIC3 senses the variation of acidic microenvironment and transmits this signal into pancreatic cancer cells, resulting in EMT to enhance migration and invasion." (PMID 28518134, 2017). "It was reported that PANC-1 and BxPC-3 pancreatic cancer cells express functional ASIC1a and ASIC3." (PMID 38175291, 2024). "In summary, although this study provided a first indication that ASIC1a and ASIC3 might be involved in epithelial-mesenchymal transition (EMT) in pancreatic cancer cells, many questions regarding the specific role of ASICs remain open." (PMID 38175291, 2024). "In addition, ASIC1 and ASIC3 contribute to epithelial-mesenchymal transition of pancreatic cancer cells." (PMID 29057936, 2017). "In addition, ASIC1 and ASIC3 are positively correlated with expression of mesenchymal marker vimentin, but inversely correlated with epithelial marker E-cadherin in pancreatic cancer cells." (PMID 28518134, 2017). "Reverse transcription-PCR (RT-PCR) and quantitative real-time RT-PCR (qRT-PCR) displayed that the mRNA of ASIC1 and ASIC3 in pancreatic cancer cell lines (PANC-1, SW1990, BxPC-3 and AsPC-1) significantly increased compared with normal pancreatic ductal cells (HPDE)." (PMID 28518134, 2017). "Moreover, ASIC1 and ASIC3 were expressed in all 40 pancreatic cancer tissues, but undetected in 6 and 4 out of 40 pancreatic noncancerous tissues, respectively." (PMID 28518134, 2017). "Furthermore, the immunofluorescence assay demonstrated that ASIC1 and ASIC3 positively correlated with the expression of mesenchymal marker Vimentin, inversely correlated with epithelial marker E-cadherin in human pancreatic cancer samples." (PMID 28518134, 2017). "Interestingly, ASIC3, which is down-regulated in lung adenocarcinoma samples, may also drive the migration of pancreatic cancer cells, so its role in cancer progression may depend on the carcinoma type." (PMID 35837090, 2022). "Therefore, ASIC1 and ASIC3 may represent exciting targets for therapeutic intervention in pancreatic cancer." (PMID 28518134, 2017). "In consistence with the results in pancreatic cancer cell lines, the immunofluorescence assay showed that ASIC1 and ASIC3 in pancreatic cancer specimens were increased compared with paired adjacent noncancerous tissues." (PMID 28518134, 2017). "Given that ASIC1 and ASIC3 are the most sensitive to acidic pHe and function as acidic pH sensors, we first detected the expression of ASIC1 and ASIC3 in pancreatic cancer cells." (PMID 28518134, 2017).
pancreatic cancer (continued). "The most important new finding in this study is that ASIC1 and ASIC3 transduce the acidic pH to elevation of [Ca2+]i concentration and RhoA activity, promoting EMT of pancreatic cancer cells during acidic microenvironment." (PMID 28518134, 2017). "To further demonstrate that ASIC1/3 facilitated aggressive behavior of pancreatic cancer cells in vivo, we next used BxPC-3 cells to establish tumor xenografts with stable knockdown of ASIC1 and ASIC3, respectively." (PMID 28518134, 2017). "This study displayed that acidic pHe significantly increased [Ca2+]i of pancreatic cancer cells in a pH-dependent manner, which was repressed by the inhibition of ASIC1 and ASIC3." (PMID 28518134, 2017). "Immunohistochemical results showed that ASIC1 or ASIC3 were much more extensively expressed in pancreatic cancer tissues than that in paired adjacent noncancerous tissues." (PMID 28518134, 2017). "ASIC1 and ASIC3 mRNA in pancreatic cancer tissues were significantly higher than that in paired noncancerous pancreatic tissues." (PMID 28518134, 2017). "As our previous results showed that the enhanced migration and invasion of pancreatic cancer cell in acidity were attributed to the acidity-induced EMT, we further investigated whether ASIC1 and ASIC3 contributed to the acidity-induced EMT." (PMID 28518134, 2017). "Inhibition of ASIC1 and ASIC3 with siRNA or pharmacological inhibitor significantly decreased [Ca2+]i and its downstream RhoA during acidity and, thus, suppressed acidity-induced epithelial–mesenchymal transition (EMT) of pancreatic cancer cells." (PMID 28518134, 2017). "ASIC1 and ASIC3 are mainly expressed on the membrane of pancreatic cancer cells and upregulated in pancreatic cancer tissues, and ASIC1 and ASIC3 promote acid-induced EMT of pancreatic cancer by activating the Ca2+/RhoA pathway, leading to the metastasis of pancreatic cancer." (PMID 38505262, 2024).